TPO (thyroid peroxidase)
Diseases named in the same sentence as TPO in open-access papers (continued):
Sharing a sentence is not in itself a finding about the gene and the disease.
Stroke (8 papers, 2012 to 2025). Sudden impairment of blood flow to a part of the brain due to occlusion or rupture of an artery to the brain. "While the TPO-RAs are effective in raising platelet counts, they have also been shown to be linked with adverse events (AEs), such as stroke." (PMID 40091091, 2025). "Our secondary outcomes were to determine stroke type associated with thrombopoietin receptor agonists (TPO-RAs) in ITP patients, as well as risk factors associated with stroke in ITP and iTTP patients." (PMID 40091091, 2025). "ITP patients who experienced stroke as an adverse event (AE) from TPO-RAs had an AIS prevalence of 1.8% (95% CI 0.6%-3.4%) and an ICH prevalence of 2.0% (95% CI 0.2%-5.3%)." (PMID 40091091, 2025). "A significant [area under the curve: 0.729 (0.540–0.919)] efficacy of the anti-TPO 10 cut-off value was observed in the differentiation of patients with stroke localization from the anterior and posterior systems." (PMID 39230146, 2024). "A significant [area under the curve: 0.724 (0.518–0.930)] effectiveness of the anti-TPO value was observed in the differentiation of patients with stroke localization from the anterior and posterior systems." (PMID 39230146, 2024). "In this study, in which we investigated the relationship of anti-TPO with strokes in the anterior and posterior circulation regions of the brain, we found that anti-TPO levels were higher in strokes in the anterior circulation systems." (PMID 39230146, 2024). "The anti-TPO value was significantly lower in the group with stroke localization in the posterior system than in the group with stroke localization in the anterior system." (PMID 39230146, 2024). "AIS (1.8%) and ICH (2.0%) prevalence in ITP patients treated with TPO-RAs was comparable to the overall ITP cohort, suggesting no significant increase in stroke risk due to TPO-RAs." (PMID 40091091, 2025). "This study exhibits that anti-TPO levels are associated with stroke with anterior circulation involvement, independent of thyroid functions." (PMID 39230146, 2024). "Importantly, the study sample included participants with a wide range of TPO, including nine participants who were at least 10 years out from their last stroke." (PMID 36827514, 2023). "In this respect, in our study showing that anti-TPO positivity is at high titers in patients with stroke with anterior system involvement, we think that interventions to reduce autoimmunity against the thyroid gland may also prevent the recurrence of a new stroke that may develop." (PMID 39230146, 2024). "This interpretation is inagreement with our regression analysis results where damage to the left TPO-STG wasthe strongest predictor of spontaneous singing performance, beyond stroke-relatedvariables." (PMID 35174327, 2022). "The prevalence of AIS, ICH, and total stroke was not significantly different in ITP patients treated with TPO-RAs when compared to ITP patients not treated with TPO-RAs (p = 0.88, p = 0.79, and p = 0.37, respectively)." (PMID 40091091, 2025). "The small numeric values of patients, the fact that the patient diagnosed with stroke had brain imaging at the time of diagnosis, and the lack of serial measurements of anti-TPO values with previous imaging methods can be considered limitations." (PMID 39230146, 2024). "The relationship between one of these antibodies, anti-TPO, and stroke localization has not been clearly demonstrated." (PMID 39230146, 2024). "Additionally, ITP patients experienced a similar prevalence of stroke regardless of if they were specifically denoted to have been treated with TPO-RAs or not, supporting the continued use of TPO-RAs in management." (PMID 40091091, 2025). "The aim of this work is to investigate whether there is a relationship between the site of stroke involvement and the anti-thyroid peroxidase antibody (anti-TPO) or not." (PMID 39230146, 2024).
Stroke (continued). "At the anti-TPO 10 cut-off value, the sensitivity was 70.0%, the positive prediction was 50.0%, the specificity was 75.9%, and the negative prediction was 88.0% in separating patients with stroke localization from the anterior and posterior systems." (PMID 39230146, 2024). "Therefore, we retrospectively analyzed our AIS patients with euthyroidism and compared the stroke severity between the two groups with or without elevated thyroid peroxidase antibody (TPO-Ab) and thyroglobulin autoantibody (Tg-Ab) in China." (PMID 35256895, 2022). "Thus, while TPO does not appear to be a prognostic factor for immediate treatment response, future research must determine whether time from stroke is an influential factor for long-term maintenance of therapeutic effects." (PMID 36827514, 2023). "Prevalence of stroke did not significantly differ between all ITP patients and those treated with TPO-RAs." (PMID 40091091, 2025).
systemic lupus erythematosus (8 papers, 2014 to 2025). An autoimmune multi-organ disease typically associated with vasculopathy and autoantibody production. "Although lesser ODs were detected for ANA, TG2, TG6, heparin, α-myosin, chondroitin sulfate, Lupus RO-60, fibrinogen, tyrosinase, β catenin, thyroid peroxidase, claudin 7, sulfatides, somatotropin, S100B, somatostatin and actin, their p values were still very, very significant." (PMID 37845267, 2023). "There is an association between PCOS and autoimmune diseases, such as anti-nuclear antibody (ANA) and anti-TPO that have been documented in systemic lupus erythematosus (SLE) and Hashimoto thyroiditis, respectively." (PMID 34444016, 2021).
type 2 diabetes (8 papers, 2013 to 2025). "Some studies have shown increased rates of anti-TPO among patients with LADA compared to among patients with type 2 diabetes." (PMID 34033299, 2021). "Four of the 5 patients (80.0%) with LADA and 11.9% of the type 2 diabetes patients tested positive for thyroid peroxidase antibodies (anti-TPO) (p = 0.001)." (PMID 34033299, 2021).
anaplastic thyroid cancer (7 papers, 2008 to 2025). "However, concomitant loss of Pten (KrasG12D/Pten− /−/TPO-cre) leads to FTCs, which rapidly progress to poorly differentiated thyroid cancer and anaplastic thyroid cancer (ATC)." (PMID 27127178, 2016).
autoimmune encephalitis (7 papers, 2017 to 2024). Inflammation of the brain secondary to an immune response triggered by the body itself. "Some published articles in literature show cases of autoimmune encephalitis diagnosed based on specific anti-neuronal antibodies, which also show an association with elevated levels of anti-TPO or anti-Tg antibodies." (PMID 37745658, 2023). "In 2020, Mattozzi etal. reported the poor disease specificity of the TPO antibody, clearly demonstrating that detection of TPO antibody positivity rate was similar amongst groups with suspected autoimmune encephalitis compared to control patients." (PMID 34159318, 2021). "Comprehensive laboratory testing, thyroid peroxidase, thyroglobulin antibodies, and autoimmune encephalitis panel were negative." (PMID 38274926, 2023).
chronic spontaneous urticaria (7 papers, 2011 to 2026). "This research has discovered a robust association between serum anti-TPO antibodies and the occurrence of chronic spontaneous urticaria." (PMID 37378208, 2023). "This study highlights the significant association between serum anti-TPO antibodies and chronic spontaneous urticaria." (PMID 37378208, 2023). "In particular, individuals with chronic spontaneous urticaria are more likely to test positive for TPO antibodies." (PMID 37378208, 2023). "Immunoglobulin (Ig) E autoantibodies against TPO have been demonstrated in chronic spontaneous urticaria (CSU) patients in higher frequency than healthy subjects." (PMID 34983483, 2022). "Furthermore, IgE auto-antibodies have been detected against more than 140 self-binding antigens in AD and against TPO in chronic spontaneous urticaria." (PMID 39337081, 2024). "It has been shown that some patients with chronic spontaneous urticaria (CSU) express IgE anti-thyroid peroxidase antibodies which may lead to an autoallergic activation of mast cells and thereby inducing CSU, however, another research group showed no such correlation." (PMID 39600380, 2024).
mood disorder (7 papers, 2004 to 2025). A cognitive disorder a disturbance in which the person's mood is hypothesized to be the main underlying feature. "Other notable symptoms, including constipation, weight gain, and mood changes, were also more prevalent in SCH+ individuals, underscoring a distinct clinical profile associated with anti-TPO positivity." (PMID 39902025, 2025). "Baseline CRP, TSH, and antibodies of thyroid peroxidase (anti-TPO) were found to predict incidence of mood changes." (PMID 37090700, 2023). "Several studies have shown a positive association between the thyroid peroxidase antibody and the development of mood disorders, with a high prevalence of positive anti-TPO antibodies among patients with bipolar and unipolar disorders." (PMID 35351167, 2022). "Thus, nomograms were developed in the vaccine group to quantify the risk of mood changes and the risk of TSH increases by means of anti-TPO antibodies, TSH, and CRP values before vaccination." (PMID 37090700, 2023). "In a second study among bipolar twins, our main finding was that co-twins of a bipolar index twin (without a mood disorder) had a higher prevalence and titer of TPO-Abs as compared to healthy control twins." (PMID 28108944, 2017). "Similar to previous reports, increased rates of sero-positivity and levels of TPO-abs in relatives (offspring or co-twin) of bipolar index cases as compared to controls were observed, irrespective of the presence of a mood disorder." (PMID 28108944, 2017). "Based on our results, we do not recommend screening for TPO-Abs in BD patients and first-degree relatives, as a marker for mood disorder vulnerability." (PMID 28108944, 2017). "Subjects with at least one lifetime diagnosis of anxiety disorders or one lifetime diagnosis of mood disorders presented anti-TPO+ more frequently than subjects without mood or anxiety disorders." (PMID 15317653, 2004). "Subjects with at least one diagnosis of anxiety disorders (OR = 4.2, C.L. 95% 1.9–38.8) or mood disorders (OR = 2.9, Cl 95% 1.4–6.6, P < 0.011) were positive for serum anti-TPO more frequently than subjects without mood or anxiety disorders." (PMID 15317653, 2004). "However, we are not able to identify this subgroup of mood disorder patients since our studies do not find a direct relationship between psychopathology and the presence of TPO-Abs." (PMID 28108944, 2017).
nodular goiter (7 papers, 2015 to 2025). Goiter characterized by discrete tissue mass(es) that may or may not produce thyroid hormones. "In the groups of individuals having nodular goiter relapse and nodular goiter with rapid growth, TPO antibodies titer was statistically lower compared to the group of individuals with nodular goiter and slow growth: 44.8% and 37.5%, respectively (р<0.05)." (PMID 33072219, 2020). "Significantly higher titers of thyroperoxidase (TPO) antibodies were obtained in individuals with rapid growth by 2.6 times and with nodular goiter and slow growth by 2.4 times, compared with the control group (р<0.05)." (PMID 33072219, 2020). "Sex, age, Anti-TPO, HT, nodular goiter, volume, cystic degeneration, and calcification were not related to ipsi-LLNM in patients with PTC (P > .05)." (PMID 33663422, 2021).
venous thromboembolism (7 papers, 2018 to 2025). Occlusion of the lumen of a vein by a thrombus that has migrated from a distal site via the blood stream. "TPOX is located in 2p25.3, in intron 10 of the human thyroid peroxidase gene; its genotypes 9 and 12, in their homozygous form, can act as risk factors for venous thromboembolism." (PMID 38027043, 2023). "And another meta-analysis of three large, population-based observational studies concluded that the risk of arterial and venous thromboembolism should be considered when evaluating the risk of thromboembolism attributed to ITP treatments (e.g. TPO-RAs)." (PMID 29856837, 2018). "Previously, our research group reported the contributions of two tetranucleotide polymorphisms with venous thromboembolism: (i) in thyroid peroxidase gene (TPO), and (ii) in the von Willebrand factor (vWA) gene, suggesting a possible contribution to atherothrombosis." (PMID 32218930, 2020). "Studies have shown that TPO-RAs may increase the risk of venous thromboembolism (VTE)." (PMID 41403445, 2025). "Reports have suggested that the activity of the thyroid peroxidase enzyme is associated with coagulation abnormalities and vascular endothelial dysfunctions, potentially contributing to an increased thromboembolic potential, a factor linked to venous thromboembolism." (PMID 38027043, 2023). "In older individuals, a small but significant increase in venous thromboembolism was reported with TPO‐RA use." (PMID 40909397, 2025). "We did not observe any unexpected adverse events attributable to TPO-RA, and no venous thromboembolism events were observed." (PMID 37335880, 2023).
angioedema (6 papers, 2014 to 2026). Swelling involving the deep dermis, subcutaneous, or submucosal tissues, representing localized edema. "One of these, termed the “autoimmune cluster” exhibited hallmark features of type IIb (autoimmune) CSU, including high ANA (52.3%) and IgG–anti-TPO (39.8%) positivity, female predominance (92%), and frequent angioedema (77%)." (PMID 41608596, 2026). "Clinically useful phenotyping draws on a small set of parameters: presence of angioedema, coexisting CIndU, autoimmune markers (for example anti-TPO or a positive ASST/BAT), total IgE level, comorbid conditions, and observed treatment response." (PMID 41608596, 2026). "Clinical parameters included disease severity, disease subtype, antihistamine response, IgE levels, anti-TPO status, gastrointestinal symptoms, and angioedema." (PMID 42072774, 2026). "By contrast, patients with serum autoreactivity (positive ASST or anti-TPO) had more angioedema and higher rates of psychiatric comorbidities." (PMID 41608596, 2026). "Compared with corresponding negative phenotype subgroups, CSU patients with elevated tIgE, positive anti-TPO IgG, positive anti-TG IgG, angioedema, UASday > 4, or recurrent CSU possessed phenotype-specific DMPs." (PMID 34539625, 2021). "For the ultimate care of patients, determining disease activity at baseline and paying attention to the laboratory markers such as CRP, total IgE and IgG-anti-TPO as well as clinical markers such as female gender and angioedema might be of special importance." (PMID 35853771, 2022).
Cognitive impairment (6 papers, 2016 to 2025). Abnormal cognition is characterized by deficits in thinking, reasoning, or remembering. "The results demonstrated a strong direct correlation between cognitive impairment as measured by the MMSE test and the levels of TSH, fT4, anti-TG and anti-TPO antibodies, 25-OH vitamin D, and brain-derived neurotrophic factor (BDNF)." (PMID 39768799, 2024). "Patients with HE often exhibit elevated levels of anti-thyroid antibodies, including anti-thyroid peroxidase (anti-TPO) and anti-thyroglobulin antibodies, which can cross-react with brain structures, leading to cognitive impairment and a range of neuropsychiatric manifestations." (PMID 41292369, 2025).
encephalitis (6 papers, 2011 to 2025). An acute inflammatory process affecting the brain parenchyma. "One patient had a paraneoplastic condition, and the encephalitis in three patients was confirmed to be associated with anti-thyroid peroxidase (TPO) or anti-GAD65 autoantibodies." (PMID 32668612, 2020). "In our previous study of 117 patients with anti-LGI1 encephalitis, we found that abnormal thyroid function was frequent in this group: 31.6% (37/117) showed abnormal thyroid function, and 22% of these had elevated levels of serum thyroid peroxidase antibodies." (PMID 35222399, 2022). "Unlike recently reported two non-tumor associated anti-NMDAR encephalitis cases with anti-TPO and infectious serology concurrence, the patient had complete clinical recovery both on discharge and one year later, which may also due to timely tumor resection." (PMID 22126669, 2011). "Although recent studies showed few patients with non-tumor-associated anti-NMDAR encephalitis have evidence of elevated anti-thyroid peroxidase (anti-TPO) antibodies, there is lack of anti-NMDAR and anti-TPO antibodies combined follow-up in details in current literatures." (PMID 22126669, 2011). "In the present case, serum anti-TPO antibodies remained elevated one year after discharge, despite resolution of clinical symptoms, further suggesting that the likely diagnosis in this case was anti-NMDAR encephalitis." (PMID 22126669, 2011).
melanoma (6 papers, 2022 to 2025). A malignant, usually aggressive tumor composed of atypical, neoplastic melanocytes. "Autoantibodies, including anti-PD-1 and thyroid-stimulating hormone (TSH)/thyroid peroxidase (TPO) antibodies, have been associated with endocrine and thyroid irAEs in melanoma and NSCLC patients." (PMID 41239350, 2025). "Previous reports have shown that the development of thyroid dysfunction was significantly associated with positive Tg Ab and/or TPO Ab before ICI therapy in patients with NSCLC, melanoma, and renal cell carcinoma." (PMID 35247869, 2022).
polycystic ovary syndrome (6 papers, 2014 to 2025). A disorder that manifests as multiple cysts on the ovaries. "The prevalence of positive thyroid peroxidase antibodies among women with polycystic ovarian syndrome is similar to other studies done in similar settings." (PMID 38289756, 2023). "Patients who received thyroid hormone supplementation for initial TSH levels > 2.5 μIU/ml achieved pregnancy and revealed increased TPO-Ab and TG-Ab levels as well as polycystic ovary syndrome significantly more often." (PMID 24708845, 2014). "However, the stratified effects of anti-TPO across age groups, body mass index (BMI) categories, and polycystic ovary syndrome (PCOS) status remain unclear." (PMID 41303060, 2025).
thyroid dysgenesis (6 papers, 2016 to 2022). "These cases of patients also show that different PAX8 mutations may cause different thyroid phenotypes of thyroid dysgenesis, which is well explained by the different effects of D94N and G41V on the transcribing activity and binding ability of PAX8 at the promoters of the target genes TPO and TG." (PMID 28060725, 2017).
allergies (5 papers, 2013 to 2025). "Studies have shown that some CSU patients have IgE antibodies targeting the TPO enzyme, potentially leading to mast cell activation and histamine release, similar to classical allergic reactions." (PMID 40075855, 2025). "In CSU the type I reaction or auto allergic CSU (aaCSU) also accounts for the majority of cases, but in contrast to classic allergies the allergen is an autoallergen, e.g., thyroid peroxidase (TPO) or interleukin (IL)-24." (PMID 37511088, 2023). "Two out of 10 and 6 of 29 patients examined were positive for anti-TG autoantibodies, 2 of 8 and 0 of 19 patients examined were positive for anti-TPO antibodies, and four and six had histories of allergies (due to drugs, foods, bees, or pollen) in periods A and B, respectively." (PMID 39280362, 2024).